COQ10B (coenzyme Q10B)
Description:
Required for the function of coenzyme Q in the respiratory chain. May serve as a chaperone or may be involved in the transport of Q6 from its site of synthesis to the catalytic sites of the respiratory complexes (By similarity).
Synonyms: FLJ13448
Tractability: Antibody: UniProt places it where antibodies can reach, with medium confidence. PROTAC: ubiquitination databases record sites on it; its protein half-life has been measured.
Gene: Protein-coding gene on chromosome 2 (197,453,493 to 197,475,310, forward strand). Ensembl gene ENSG00000115520.
Subcellular location: Mitochondrion inner membrane
Subcellular location (Human Protein Atlas): Cytosol
Pathways (Reactome):
Metabolism: Complex IV assembly; Respiratory electron transport
Gene Ontology:
Molecular function: ubiquinone binding
Biological process: cellular respiration
Cellular component: mitochondrion; mitochondrial inner membrane
Genetic constraint (gnomAD): Loss-of-function variants: 1 observed, 4.08 expected, observed/expected ratio (o/e) 0.24, 90% interval 0.086 to 1.15. That is too few expected variants to judge how well the gene tolerates losing a copy. Missense variants: 112 observed, 111.21 expected, observed/expected ratio (o/e) 1.01, 90% interval 0.86 to 1.18. Synonymous variants: 51 observed, 45.05 expected, observed/expected ratio (o/e) 1.13, 90% interval 0.9 to 1.43.
Homologues: Orthologues: chimpanzee COQ10B (99% identical), macaque COQ10B (97% identical), rabbit COQ10B (92% identical), dog COQ10B (91% identical), pig COQ10B (91% identical), rat Coq10b (86% identical), mouse Coq10b (85% identical), guinea pig COQ10B (84% identical), zebrafish coq10b (69% identical), Drosophila melanogaster CG9410 (39% identical), Caenorhabditis elegans R144.13 (32% identical). Paralogues in human: COQ10A (63% identical).
Diseases named in the same sentence as COQ10B in open-access papers:
COQ10B is named in the same sentence as 5 diseases in open-access papers, as found by Europe PMC text mining. Sharing a sentence is not in itself a finding about the gene and the disease. The quoted sentences say what the papers report.
schizophrenia (2 papers, 2021 to 2023). A major psychotic disorder characterized by abnormalities in the perception or expression of reality. "As expected because of low sensitivity, this study identified only seven placental genes associated with schizophrenia, three of which are nonetheless replicated in our dataset (COQ10B, placenta-specific, and VPS29 and SEC11A, also associated with schizophrenia in brain)." (PMID 37188697, 2023).
breast carcinoma (1 paper, 2021). "We consulted the Human Protein Atlas Interactive Analysis to validate the expression of the core driver genes, including IDI1, BNIP3, IFRD1, COQ10B, and ZBTB10, at the protein and RNA levels in breast cancer." (PMID 34226298, 2021).
depression (1 paper, 2024). "Ten genes were associated with depression, ICV, and the volume of the hippocampus, among them Heat Shock Protein Family E (Hsp10) Member 1 (HSPE1), MOB Family Member 4, Phocein (MOB4), and Coenzyme Q10B (COQ10B)." (PMID 40800518, 2024).
glioma (1 paper, 2023). A benign or malignant brain and spinal cord tumor that arises from glial cells (astrocytes, oligodendrocytes, ependymal cells). "By using western blot evaluation, we were able to identify changes in FSP1 and COQ10B protein expression in glioma cells, which were crucial to the proliferative of these cancerous cells." (PMID 37848823, 2023).
prostate carcinoma (1 paper, 2020). A carcinoma that arises from epithelial cells of the prostate gland. "COQ10B has not been associated with prostate cancer previously according to the NCBI GWAS Catalog." (PMID 32986714, 2020).